NAT10 (N-acetyltransferase 10)
Diseases named in the same sentence as NAT10 in open-access papers (continued):
Sharing a sentence is not in itself a finding about the gene and the disease.
non-small cell lung carcinoma (10 papers, 2022 to 2025). A group of at least three distinct histological types of lung cancer, including non-small cell squamous cell carcinoma, adenocarcinoma, and large cell carcinoma. "Previous research has also revealed that NAT10 is significantly upregulated in non-small cell lung cancer, where it promotes tumor progression." (PMID 40860186, 2025). "Interestingly, we identified c-Myc as the downstream target of β-catenin, and based on the most recent study on non-small cell lung cancer, there remains the possibility that the transcriptional activation of NAT10 might be modulated by c-Myc in CRC." (PMID 36522719, 2022). "Furthermore, NAT10 modulates GAS5 expression and mediates its ac4C modification in non-small cell lung cancer (NSCLC), whereas GAS5 facilitates immune cell infiltration by activating the type I interferon signaling pathway." (PMID 41316475, 2025). "In non-small cell lung cancer, c-myc-mediated upregulation of NAT10 promotes the proliferative and migratory abilities of non-small cell lung cancer cells." (PMID 41316475, 2025).
esophageal cancer (9 papers, 2024 to 2025). A primary or metastatic malignant neoplasm involving the esophagus. "This group showed that NAT10 is overexpressed in esophageal cancer tissues and is associated with disease prognosis." (PMID 38233930, 2024). "For example, NAT10 enhances the metastasis of esophageal cancer by stabilizing NOTCH3 mRNA via ac4C modification." (PMID 40999468, 2025). "For example, NAT10 enhances EGFR translation efficiency in esophageal cancer by enriching ac4C-modified tRNAs, thereby activating MAPK/ERK signaling." (PMID 40588654, 2025). "Downstream, NAT10 increases NOTCH3 mRNA stability via ac4C acetylation to promote esophageal cancer metastasis." (PMID 40881352, 2025). "In esophageal cancer, NAT10-mediated ac4C modification of tRNA boosts the translational efficiency of Epidermal Growth Factor Receptor (EGFR) mRNA." (PMID 40881352, 2025). "Overall, the results unveil a novel role of ac4C modifications in regulating lysosomal acidification and propose a potential strategy by targeting NAT10 to inhibit esophageal cancer metastasis." (PMID 40729677, 2025). "Depleting NAT10 in conjunction with gefitinib can synergistically hinder the progression of esophageal cancer." (PMID 39791162, 2025). "In esophageal cancer, NAT10 overexpression is further up-regulated in primary cancer and metastatic tissues through CTC-490G23.2 lncRNA acetylation, promoting tumor invasion and metastasis." (PMID 38233930, 2024). "In esophageal cancer, NAT10 enhances the abundance of ac4 C-modified tRNAs and further enhances the translation efficiencies of EGFR, which is a member of receptor tyrosine kinase family and is activated by various ligands to mediate various cellular activities to promote cancer progression." (PMID 40588654, 2025). "NAT10 plays a role in the resistance to gefitinib in treating esophageal cancer." (PMID 39791162, 2025). "In esophageal cancer, NAT10 is identified as a substrate of 2-hydroxyisobutyrylation (Khib)." (PMID 40881352, 2025). "The oncogenic mechanism of NAT10 in esophageal cancer (ESCA) has been extensively investigated." (PMID 39640362, 2024). "The combined depletion of NAT10 and treatment with the EGFR small-molecule inhibitor gefitinib synergistically inhibits esophageal cancer progression both in vitro and in vivo." (PMID 40881352, 2025). "NAT10‐mediated ac4C acetylation of tRNA promotes EGFR translation and gefitinib resistance in esophageal cancer." (PMID 39640362, 2024). "The team found that NAT10 catalyzes ac4C formation in CTC-490G23.2 lncRNA, inducing transcript expression in primary esophageal cancer and metastatic tissues." (PMID 38233930, 2024).
Sepsis (9 papers, 2022 to 2025). Sepsis is defined as life-threatening organ dysfunction caused by a dysregulated host response to infection. "The mechanism underlying the regulation of NAT10 in infectious diseases was reported in sepsis and in virus replication and reactivation." (PMID 40588654, 2025). "Next, we further investigated whether the therapeutic effects NAT10 over-expression were associated with the pyroptosis of neutrophils, which has been considered as a major driver of the development of sepsis." (PMID 36068299, 2022). "In neutrophils, NAT10 has been reported as an important negative regulator of pyroptosis; downregulation of NAT10 exacerbates sepsis by increasing pyroptosis in neutrophils via the ULK1-STING-NLRP3 axis." (PMID 40362562, 2025). "The decreased expression of NAT10 in neutrophils contributes to the progress of sepsis by promoting neutrophil pyroptosis." (PMID 40588654, 2025). "NAT10 was also found promoting sepsis-induced pulmonary injury by mediating ac4C acetylation of TFRC mRNA." (PMID 40588654, 2025). "In this way, NAT10 was involved in sepsis related complications and contributing to the occurrence and progression of complications." (PMID 40588654, 2025). "In infectious contexts, NAT10 influences sepsis progression and viral pathogenesis by stabilizing pathogen-related RNAs, while in cardiovascular diseases, it exacerbates myocardial injury and heart failure through ac4C-dependent and independent pathways." (PMID 40588654, 2025). "Research indicates that the neutrophil-specific NAT10 contributes to the progress of sepsis, and revealing a potential therapeutic target of downstream pathways for sepsis." (PMID 40588654, 2025). "NAT10 mediated ac4C modification of ULK1 also regulates neutrophil pyroptosis in sepsis by activating STING pathway." (PMID 38689229, 2024). "A previous study reveals that downregulation of NAT10 exacerbates pyroptosis, thus promoting the progression of sepsis." (PMID 39251905, 2024). "Of note, it was recently reported that NAT10 regulates pyroptosis in sepsis through the acetylation of ULK1 RNA in the STING pathway via the ULK1-STING-NLRP3 axis." (PMID 37237981, 2023). "Via this murine model, we found that NAT10 functions as a negative regulator of neutrophils pyroptosis and a protective factor of sepsis, indicating its potential value in sepsis treatment via restraining neutrophil pyroptosis." (PMID 36068299, 2022). "More importantly, lower level NAT10 is also found in neutrophils from sepsis patients, compared to those from the healthy controls, which is positively correlated with disease severity." (PMID 36068299, 2022). "Accordingly, these data reveal the decreased expression pattern of NAT10 and its specific RNA modification ac4C in sepsis neutrophils." (PMID 36068299, 2022). "The enzyme N-acetyltransferase NAT10 is a negative regulator of neutrophil pyroptosis and its downregulation contributes to the progress of sepsis by exacerbating pyroptosis via the ULK1-STING-NLRP3 pathway." (PMID 36068299, 2022). "In conclusion, the current study described the negative regulation of NAT10 on neutrophil pyroptosis and its protective role in sepsis." (PMID 36068299, 2022). "Consistently, NAT10 was found significantly expressed lower in neutrophils of sepsis patients, compared to healthy controls." (PMID 36068299, 2022). "In other words, the downregulation of NAT10 in neutrophils contribute to the progress of sepsis by exacerbating pyroptosis in neutrophils via promoting the ULK1-STING-NLRP3 axis." (PMID 36068299, 2022). "The decreased expression of NAT10 are also observed in sepsis patients and its correlation with clinical severity is found." (PMID 36068299, 2022). "Neutrophils-specific over-expression of NAT10 improved the survival and ameliorated lung injury in sepsis mice by diminishing pyroptosis." (PMID 36068299, 2022). "Clinically, the decreased expression of NAT10 and its correlation with clinical severity were also observed in sepsis patients." (PMID 36068299, 2022).
Sepsis (continued). "It is found that pyroptosis in sepsis neutrophils was diminished in NAT10-OE mice, indicated by the downregulated expression of pyroptosis molecules and cytokines." (PMID 36068299, 2022). "Collectively, neutrophil-specific over-expression of NAT10 can ameliorate sepsis lethality by restraining neutrophil pyroptosis, indicating the potential regulatory role of NAT10 in neutrophil pyroptosis and sepsis pathogenesis." (PMID 36068299, 2022). "Our findings extended the understanding about NAT10 on sepsis-induced diseases, indicating that NAT10 might be a promising therapeutic target." (PMID 39251905, 2024). "The regulatory role of NAT10 in sepsis has been reported before." (PMID 39251905, 2024). "In addition, NAT10 has also been found to be closely related with other complications of sepsis, such as skeletal muscle atrophy." (PMID 39251905, 2024). "Interestingly, a recent study indicates that NAT10 expression is reduced in patients with sepsis and correlated with clinical severity." (PMID 39251905, 2024). "Genes associated with hub RMGs may linked to the progression of sepsis, NOP2 and NAT10 were co-expressed, and previous research reported that NAT10 improves the survival and ameliorates lung injury in septic mice by inhibiting neutrophil pyroptosis." (PMID 37701433, 2023). "Collectively, our findings disclose that NAT10 is a negative regulator of neutrophil pyroptosis and its downregulation contributes to the progress of sepsis by exacerbating pyroptosis via the ULK1-STING-NLRP3 axis, therefore revealing a potential therapeutic target for sepsis." (PMID 36068299, 2022). "Finally, to determine the role of ULK1-mediated STING-NLRP3 axis in NAT10-dependent alleviation of sepsis, STING inhibitor C-176 was administered to wild type sham or CLP-induced septic mice." (PMID 36068299, 2022). "While over-expressing NAT10 in neutrophils can ameliorate lethality of sepsis." (PMID 36068299, 2022). "We then investigated the role of NAT10 insufficiency in the development of sepsis." (PMID 36068299, 2022). "Here, we demonstrated that NAT10 is an important negative regulator of neutrophil pyroptosis, whose expression remarkably decreased in sepsis and contributed to the excessive pyroptosis in sepsis neutrophils." (PMID 36068299, 2022). "Thus, our findings uncover a critical mechanism that regulates neutrophil pyroptosis and indicate the potential of neutrophils and NAT10 as cellular and molecular targets in sepsis intervention." (PMID 36068299, 2022). "In some extent, this gives us hints on the participation of NAT10 in sepsis development." (PMID 36068299, 2022). "Therefore, the role and mechanism of NAT10 in neutrophil pyroptosis demonstrated in the study not only provide insights into the pathogenesis of sepsis, but also harbor the potential to prevent or treat sepsis via regulating neutrophil pyroptosis." (PMID 36068299, 2022). "Therefore, our data indicate that the therapeutic effect of neutrophil-specific NAT10 over-expression on sepsis by inhibiting pyroptosis is mediated by the ULK1-STING-NLRP3 axis." (PMID 36068299, 2022). "NAT10 inhibition could alleviate sepsis-induced pulmonary injury." (PMID 40588654, 2025). "Finally, we established the sepsis-induced ALI rat model to explore the role of NAT10 in vivo." (PMID 39251905, 2024).
acute myeloid leukemia (8 papers, 2020 to 2025). Acute myeloid leukemia (AML) is a group of neoplasms arising from precursor cells committed to the myeloid cell-line differentiation. "NAT10 regulates the malignant proliferation of acute myeloid leukemia (AML) cells by targeting the cell cycle and inhibiting apoptosis." (PMID 39640362, 2024). "NAT10 is overexpressed in various tumour types, including hepatocellular carcinoma, colorectal cancer, melanoma, esophageal cancer, acute myeloid leukaemia (AML), among others." (PMID 38880983, 2024). "NAT10 is also a potential biomarker in acute myeloid leukemia (AML); however, the mechanisms underlying NAT10’s contribution to disease states and the effect of targeting NAT10 as a therapeutic target remain unclear." (PMID 33425753, 2020). "In acute myeloid leukemia (AML), NAT10 knockout blocks the translational efficiency of target genes such as SLC1 A4 and HOXA9/MENIN, disrupts serine metabolic reprogramming, impairs leukemia stem cell self-renewal, and enhances chemotherapeutic sensitivity." (PMID 40588654, 2025). "Besides, NAT10 was reported to could inhibit cell apoptosis in acute myeloid leukemia by strengthening ERS." (PMID 36765042, 2023). "Moreover, NAT10 can enhance endoplasmic reticulum stress (ERS) and inhibit acute myeloid leukemia (AML) cell apoptosis." (PMID 39817252, 2025). "Additionally, some studies also found that ERS is considered to have tumorigenic and immunosuppressive effects in cancer, and NAT10 can enhance ERS and inhibit cell apoptosis in acute myeloid leukemia." (PMID 36765042, 2023).
lymph node metastasis (7 papers, 2017 to 2025). "NAT10 expression levels are closely related to adverse clinical features such as advanced T stage, lymph node metastasis, and low overall survival." (PMID 39764566, 2025). "Similar research indicates that NAT10, the only known “writer” of ac4C mRNA modification, is highly expressed in HNSC patients with lymph node metastasis, and this elevated expression is closely associated with poorer prognosis in patients." (PMID 39764566, 2025). "Our study revealed that NAT10 expression was associated with tumor stage, lymph node metastasis, vascular invasion and distant metastasis in patients with CRC and a higher NAT10 expression level implied a poorer prognosis." (PMID 36522719, 2022). "Multivariate analysis by cox-regression revealed that NAT10 expression, tumor number, microvascular invasion, and lymph node metastasis were independent prognostic factors of OS." (PMID 28859621, 2017). "Univariate analysis by Cox-regression revealed that 5 prognostic factors affecting OS: NAT10 expression level, tumor size, tumor number, microvascular invasion and lymph node metastasis." (PMID 28859621, 2017). "High NAT10 level correlated with advanced T stage, lymph node metastasis and poor overall survive." (PMID 38826095, 2024). "In addition, NAT10 levels positively correlate with tumor aggressiveness, and patients with lymph node metastasis have elevated NAT10 protein." (PMID 38233930, 2024). "Additionally, high NAT10 expression correlated with advanced T stage and lymph node metastasis." (PMID 38826095, 2024). "Our current investigation evidenced heightened NAT10 expression in NSCLC compared to adjacent normal tissues, correlating with T stage, lymph node metastasis, and dismal prognosis." (PMID 38826095, 2024). "Specifically, clinical subgroup analysis demonstrated that the N1 + N2 group with lymph node metastasis, M1 group with distant metastasis, and III + IV tumor stage group showed higher NAT10 expression levels, implying that NAT10 can regulate CRC proliferation and metastasis." (PMID 36522719, 2022).
myocardial infarction (7 papers, 2022 to 2026). Gross necrosis of the myocardium, as a result of interruption of the blood supply to the area, as in coronary thrombosis. "NAT10-mediated ac4C modification has been linked to several human diseases, including depression, myocardial infarction, interstitial cystitis, and acquired immune deficiency syndrome (AIDS)." (PMID 40779453, 2025). "NAT10 contributes to the pathological progression of cardiovascular diseases, including myocardial infarction and heart failure." (PMID 40588654, 2025). "Accumulating evidence suggests that NAT10-mediated ac4C modification is involved in the pathogenesis of various diseases, such as osteogenesis, myocardial infarction, tumor progression, cardiac remodeling, and inflammation." (PMID 41291301, 2025). "In our study, we activated fibroblasts in vitro using TGF‐β1 (20 ng/mL), followed by establishing a myocardial infarction mouse model to evaluate the impact of NAT10 on collagen synthesis and cardiac fibroblast proliferation." (PMID 39482983, 2024). "According to the results of this study, it is anticipated that NAT10 will emerge as a novel therapeutic target for mitigating myocardial fibrosis following myocardial infarction." (PMID 39482983, 2024). "Through the administration of Remodelin, we effectively reduced cardiac fibrosis in myocardial infarction mice by inhibiting NAT10's ability to acetylate mRNA." (PMID 39482983, 2024). "We further demonstrate that overexpression of Nat10 in cardiomyocytes enhances cardiomyocyte proliferation and improves heart function after myocardial infarction (MI)." (PMID 38459019, 2024). "In this study, it was observed that NAT10, the enzyme responsible for ac4C modification, exhibits a significant increase in expression in myocardial fibrosis tissues induced by myocardial infarction and CFs stimulated by TGF‐β1." (PMID 39482983, 2024). "In myocardial infarction, NAT10 may take part in promoting the cardiomyocyte death and myocardial fibrosis to exacerbate cardiac injury." (PMID 40588654, 2025). "Based on our research findings, we have discovered that the upregulation of NAT10 expression subsequent to myocardial infarction not only serves as a catalyst for cardiomyocyte apoptosis via the ferroptotic pathway but also exerts a suppressive influence on the apoptosis of CFs." (PMID 39482983, 2024). "Furthermore, immunohistochemistry (IHC) and dot blotting analyses demonstrated that the inhibition of NAT10 resulted in the suppression of myocardial infarction (MI)‐induced upregulation of ac4C acetylation, while NAT10 expression remained unaffected." (PMID 39482983, 2024). "In order to elucidate the pathophysiological role of NAT10 in post‐myocardial infarction (MI) cardiac fibrosis, we investigated the potential involvement of NAT10 in MI‐induced cardiac fibrosis using an animal model." (PMID 39482983, 2024). "Consequently, targeting the ac4C modification capacity of NAT10 may mitigate myocardial fibrosis following myocardial infarction in mice and potentially enhance cardiac function." (PMID 39482983, 2024). "Specifically, our observations were limited to the upregulation of NAT10 in cardiac fibroblasts treated with TGF‐β1 and in myocardial tissue post‐myocardial infarction at the cellular level." (PMID 39482983, 2024).